CRP (C-reactive protein)
Diseases named in the same sentence as CRP in open-access papers (continued):
Sharing a sentence is not in itself a finding about the gene and the disease.
Sepsis (continued). "However, there were significantly higher WBC counts and CRP levels, as well as lower platelet and Hb levels in the sepsis group than in the control group." (PMID 31309103, 2019). "All patients showed swelling of affected areas, trismus, dysphagia, dyspnea, involvement of several fascial spaces, phlegmonous spread, laboratory parameters of septicemia and a C-reactive protein (CRP) above 200 mg/l with white blood cell counts greater than 19*1000/ μl at admittance." (PMID 31375095, 2019). "Our study demonstrated that only serum AGP and lactate levels, as well as maximum 24-h APACHE-II scores, were independent indexes to predict sepsis outcomes as was shown by a stepwise logistic regression model after adjusting for age, gender, CRP levels, and WBC counts." (PMID 31309103, 2019). "Its usefulness may be enhanced when it is considered in conjunction with other sepsis screen markers like CRP and WBC in ruling out sepsis." (PMID 30881431, 2019). "This response is reflected by the high CRP-level in patients with sepsis." (PMID 31581250, 2019). "Similarly, the NLR was also shown to be a more useful diagnostic tool to identify patients with septicemia than other more commonly used diagnostic blood tests such as WBC and neutrophil counts and CRP." (PMID 31428594, 2019). "Subgroup analyses did not identify any separate group that may benefit, including patients with sepsis or with elevated C-reactive protein levels." (PMID 31824644, 2019). "PCT is often reported to perform better than CRP as a maker of sepsis." (PMID 30623257, 2019). "We evaluated the accuracy of neutrophil CD64 as a biomarker for diagnosing infection in adult patients with septic syndrome based on sepsis-2 criteria, by performing a systematic literature review and a meta-analysis, comparing the diagnostic value of neutrophil CD64 with that of CRP and PCT." (PMID 30623257, 2019). "The higher content of WBC and CRP may suggest the heavier immune response in the CS presenting sepsis." (PMID 31689826, 2019). "As the level of CRP synthesis reflects the intensity of the inflammatory process, it is used as one of the clinical markers of infectious and inflammatory diseases, including sepsis." (PMID 31057785, 2019). "C-reactive protein (CRP) is a well-known marker for sepsis and/or infection." (PMID 31215423, 2019). "A CRP is an acute phase reactant and a sensitive marker when an individual has sepsis." (PMID 31065202, 2019). "Nevertheless, CRP continues to contribute to the prognosis and treatment progress monitoring in the case of sepsis, and elevated CRP levels might have a relation to the extent of the disease and the severity of the infection." (PMID 31671729, 2019). "In children with sepsis, partial correlation analyses controlling for age and gender highlighted associations between (i) SDQ scores and low lymphocyte count (r=−0.712; p=0.009, n=14), and (ii) IES-8 score and high CRP levels (r=0.823; p=0.006, n=11)." (PMID 30301824, 2018). "Moreover, leptin can act as an early acute phase reactant, similar to C-reactive protein (CRP), IL-6, and IL-1, which are released in high amounts during bacterial infection, sepsis, and inflammation." (PMID 29525910, 2018). "Thus we initiated the baby on antibiotics by intravenously administering Ampiclox (ampicillin and cloxacillin) and gentamycin until sepsis was excluded by the laboratory results of CRP, CBC, and blood culture." (PMID 30595131, 2018). "The use of CBC in combination with CRP for late-onset sepsis evaluation in VLBW infants could potentially be more sensitive than each individual test." (PMID 29382319, 2018). "Therefore, the value of CRP in the diagnosis of neonatal infection and sepsis should be reconsidered." (PMID 29968788, 2018). "In addition, through correlation analysis, this study found that there was a positive correlation between the CD64 index and CRP in the sepsis group (r = 0.6255, P = 0.0111)." (PMID 29968788, 2018).
Sepsis (continued). "Studying a broader range of CRP levels in subjects allowed us to fill in information on the relationship between inflammation and BP between the two extremes, “normal” and those with sepsis." (PMID 29855349, 2018). "Test quality of CRP levels for the prediction of parasitemia, malaria and septicemia." (PMID 30080904, 2018). "In addition, the CRP/albumin ratio showed high values of 8.7 and 5.09, respectively, in patients with severe sepsis or septic shock." (PMID 29880755, 2018). "However, compared with the CD64, WBC and CRP indices, the PCT clearly has more advantages and diagnostic value during late infection (at the phase of sepsis)." (PMID 29968788, 2018). "CRP levels often increase with elevation of PCT levels in sepsis." (PMID 29725488, 2018). "NLR and MPV values were higher and correlated with PCT and CRP in pediatric patients with sepsis." (PMID 30190753, 2018). "Moreover, CRP had 75% sensitivity and 76.3% specificity for proven sepsis with a cut-off of 0.16 mg/dL." (PMID 30068303, 2018). "Of the 500 excluded blood cultures, 481 represented repeated blood cultures done within 14 days of the initial late-onset sepsis evaluation, 9 were probable contaminants and 10 had no available associated CRP data at all three time points." (PMID 29382319, 2018). "Currently, PCT appears to be a specific alternative marker to CRP in the rapid diagnosis of sepsis." (PMID 30068303, 2018). "In a study on 334 adults with severe sepsis or septic shock, it was concluded that the C-reactive protein/albumin ratio at the time of discharge from the intensive care unit was correlated with the long-term prognosis (up to 90 days) after an episode of sepsis." (PMID 29267535, 2018). "The association between this ratio and sepsis was independent of disease severity, of potential confounding co-morbidities and of the basal inflammatory status of the patient as assessed by the CRP levels in serum and the neutrophil count in blood." (PMID 30097607, 2018). "For the diagnosis of proven sepsis, we found the cut-off of CRP 2 to be 2.6 mg/L." (PMID 30068303, 2018). "The ratio of CRP to ALB (CRP/ALB) has also recently been used to predict the prognosis of patients with severe sepsis or septic shock, with an increased CRP/ALB ratio at the intensive care unit (ICU) admission being independently associated with increased mortality rates." (PMID 30297724, 2018). "In our study, we determined the cut-off of CRP 1 to be 7.0 mg/L for proven sepsis." (PMID 30068303, 2018). "CRP is one of the most studied and utilized laboratory markers for newborn sepsis." (PMID 30068303, 2018). "In contrast to the more pro-inflammatory functions, CRP induces high levels of the anti-inflammatory IL-1 receptor antagonist, and transgenic animals overexpressing human CRP are protected from inflammatory diseases including sepsis, alveolitis, arthritis, and atherosclerosis." (PMID 30105015, 2018). "For a sepsis diagnosis their evidence looked at different CRP cut-offs from 2.5mg/L to 10mg/L for diagnosis of sepsis in babies aged under 12 hours to up to 10 days old, therefore making their final recommendation based on the increased likelihood of sepsis rather than specifically meningitis." (PMID 30509228, 2018). "CRP is an acute phase reactive protein that increases rapidly when inflammation or tissue damage occurs, and is therefore frequently utilized as a biomarker to evaluate the severity of sepsis." (PMID 30087610, 2018). "Several studies claim that C-reactive protein is of prognostic value in sepsis." (PMID 30446841, 2018). "Like in our daily practice, bandemia, serum CRP, and lactate levels could be used to diagnose sepsis or predict its severity in PD patients." (PMID 30417011, 2018). "Resistin and extracellular heat shock protein-90α (eHSP90α) (AUROC > 0.85) could better than CRP or lactate (AUROC > 0.75) discriminate sepsis from systemic inflammatory response syndrome (SIRS) (p < 0.001) in adults." (PMID 30297655, 2018).
Sepsis (continued). "PCT is usually considered to have a higher capacity than hs-CRP in the diagnosis of sepsis." (PMID 28764651, 2017). "Although DNI as a prognostic marker for sepsis might be comparable to other pro-inflammatory cytokines such as CRP and procalcitonin, DNI can change in conditions of ineffective leukocyte production." (PMID 28320333, 2017). "Use of a biomarker, such as CRP, in addition to clinical signs may help clinicians to diagnose sepsis early and to start timely treatment." (PMID 28226029, 2017). "Biomarkers such as CRP, procalcitonin, and various cytokines are elevated in sepsis." (PMID 28763506, 2017). "Our results supported that presepsin showed similar performance with CRP in sepsis diagnosis." (PMID 28875483, 2017). "Additionally, CRP has a broad abnormal range, and we demonstrated that levels at or above 74.2 mg/L should indicate the suspicion of sepsis, while levels at or above 139.4 mg/L highly suggestive of septic shock in oldest old patients." (PMID 28764651, 2017). "Our objective was to evaluate the usefulness of DNI for predicting in-hospital mortality within 30 days after surgery in patients with sepsis caused by peritonitis by means of comparing DNI, white blood cell (WBC) count, neutrophil percentage, and C-reactive protein (CRP) before and after surgery." (PMID 28763506, 2017). "Based on the results of our meta-analysis, presepsin is a promising marker for diagnosis of sepsis as PCT or CRP, but these results should be interpreted carefully and cautiously, since only a limited number of studies included and high heterogeneity between them." (PMID 28875483, 2017). "However, the same study also found that one day after sepsis onset, CRP alone was a better predictor of infection, warranting future work." (PMID 28487810, 2017). "In addition, CRP also showed statistically significant AUCs to discriminate sepsis and septic shock on each day." (PMID 28793880, 2017). "Procalcitonin, high-sensitivity C-reactive protein (hs-CRP), and lactate levels versus blood culture results in 886 adult patients admitted to the emergency department, who underwent workup for presumed bacteremia or sepsis." (PMID 29201568, 2017). "C-reactive protein (CRP) is a frequently used biomarker for clinical severe sepsis." (PMID 28842621, 2017). "Based on the results of our meta-analysis, presepsin is a promising marker for diagnosis of sepsis as PCT or CRP, but its results should be interpreted more carefully and cautiously since too few studies were included and those studies had high heterogeneity between them." (PMID 28875483, 2017). "In contrast, higher day 1 levels of TNF-α, IL-6, IL-8, and CRP (p = 0.013, p < 0.001, p = 0.001, and p = 0.017, respectively), but not IL-1β (p = 0.057), were observed in patients with septic shock compared with those with severe sepsis." (PMID 28542440, 2017). "In subjects with sepsis, CRP was higher than the laboratory ranges for healthy donors (1.5 μg/dL)." (PMID 28367457, 2017). "Therefore, the aim of this study was to evaluate the usefulness of DNI for predicting postoperative mortality in patients with sepsis caused by peritonitis by means of comparing the DNI, WBC count, neutrophil percentage, and CRP before and after surgery." (PMID 28763506, 2017). "In particular CRP has a very high specificity for identifying sepsis in the neonatal setting." (PMID 29104224, 2017). "Deceased AKI patients were statistically significantly older (P < 0.000), with higher CCI score (P < 0.000), greater prevalence of sepsis (P =0.004), higher levels of C-reactive protein (CRP) (P < 0.017) and ferritin (P < 0.051) and lower concentrations of albumin (P<0.01) compared to survivors." (PMID 27471736, 2016). "However, since pathological conditions other than sepsis (trauma, burn injury, etc.)may be associated with elevated IL-6 and/or CRP levels, the authors themselves warn about the need to rule out such conditions upon interpreting postmortem values of IL-6 and CRP." (PMID 27239102, 2016).
Sepsis (continued). "We indicated that the likelihood of sepsis was increased by increased CRP with lymphopenia." (PMID 26863002, 2016). "The mean FHR-3 levels were significantly higher in the sepsis group (1.71-fold, p = 0.0173) compared to our healthy donor cohort, but did not correlate with a classical marker for an acute phase reaction, i.e. CRP levels (rs = 0.208, p = 0.2166)." (PMID 27007437, 2016). "The aim of this study was to determine the impact of surgical interventions on the novel sepsis biomarker soluble urokinase plasminogen activator receptor (suPAR) and to compare with the routinely used laboratory parameters CRP, PCT, and IL-6 in patients with culture-proven bloodstream infection." (PMID 30671318, 2016). "The episodes involving only septicemia had a higher maximum CRP-median (median, 207 mg/L; range, 41–341 mg/L) compared with the episodes involving only respiratory viral infection (median, 80 mg/L; range, 4-332mg/L), but the difference was not statistically significant (p = 0.05)." (PMID 27309354, 2016). "In non-cirrhotic patients, serum C-reactive protein (CRP) level had been reported as the risk factor for severe sepsis in children with cancer and febrile neutropenia." (PMID 27861595, 2016). "However, the level of CRP serum levels correlate with the severity of infection and a decrease in CRP level after antimicrobial therapy in sepsis patients correlates with the effectiveness of treatment." (PMID 26761003, 2016). "Among patients in the SPD group, the main acute comorbid conditions were peripheral vascular and cardiac complications, sepsis, fractures, and cancers with an increase in serum CRP level (from 14.3 ± 18 to 132 ± 90 mg/L) and a decrease in serum albumin (from 33 ± 4.5 to 28.6 ± 4 g/L)." (PMID 27756251, 2016). "The aim of this study is to investigate the CRP and hemogram parameters as an indicator of sepsis." (PMID 26863002, 2016). "Increase in CRP levels by 2 SD was also defined as sepsis criteria in 2012 sepsis guideline." (PMID 26863002, 2016). "Due to this limited diagnostic value, CRP is not recommended in the current sepsis guidelines as a sepsis biomarker." (PMID 26761003, 2016). "Furthermore, there was a poor positive correlation between CRP and each of age and sepsis (r2 = 0.04 and r2 = 0.09)." (PMID 26863002, 2016). "However, comparing the two study groups, the sepsis survivors had low CRP values, but higher CRP values than controls, and more frequently had slightly elevated PCT." (PMID 27056672, 2016). "Sepsis was diagnosed on the basis of fever, inappropriate tachycardia, increased respiratory rate, toxic granulation with neutrophil leucocytosis, Dohle bodies in the blood smear and increased CRP levels." (PMID 26785407, 2016). "Although CRP was related with sepsis and mortality in our patients, we are of the opinion that a combined evaluation of CRP and other hemogram parameters would increase the efficiency in diagnosing sepsis." (PMID 26863002, 2016). "CRP was slightly elevated in eight sepsis survivors and seven control individuals." (PMID 27056672, 2016). "The remaining 3 episodes were considered invasive infections even though the microorganism was only isolated in low respiratory secretions, as all had severe sepsis with renal failure, metabolic acidosis, hemodynamic instability, and elevated procalcitonin and C-reactive protein levels." (PMID 27027618, 2016). "Laboratory tests available to diagnose infection and sepsis are those dating from the 1970s or older, such as neutrophil counts, identification of immature myeloid cells in the peripheral blood, and acute phase reactants like C-reactive protein (CRP)." (PMID 28097142, 2016). "The changes in CRP levels and hemogram parameters and their combinations may help to distinguish sepsis from non-sepsis SIRS." (PMID 26863002, 2016). "Furthermore, serum OPN concentrations were closely correlated to markers of systemic inflammation in critically ill and sepsis patients, such as CRP, PCT, IL-6 and TNF." (PMID 26111529, 2015).